SLX4 (SLX4 structure-specific endonuclease subunit)
Description:
Regulatory subunit that interacts with and increases the activity of different structure-specific endonucleases. Has several distinct roles in protecting genome stability by resolving diverse forms of deleterious DNA structures originating from replication and recombination intermediates and from DNA damage. Component of the SLX1-SLX4 structure-specific endonuclease that resolves DNA secondary structures generated during DNA repair and recombination. Has endonuclease activity towards branched DNA substrates, introducing single-strand cuts in duplex DNA close to junctions with ss-DNA. Has a preference for 5'-flap structures, and promotes symmetrical cleavage of static and migrating Holliday junctions (HJs). Resolves HJs by generating two pairs of ligatable, nicked duplex products. Interacts with the structure-specific ERCC4-ERCC1 endonuclease and promotes the cleavage of bubble structures. Interacts with the structure-specific MUS81-EME1 endonuclease and promotes the cleavage of 3'-flap and replication fork-like structures. SLX4 is required for recovery from alkylation-induced DNA damage and is involved in the resolution of DNA double-strand breaks.
Synonyms: BTBD12; KIAA1784; KIAA1987; FANCP; MUS312
Tractability: Small molecule: a structure with a bound ligand is known. PROTAC: UniProt records ubiquitination sites on it; ubiquitination databases record sites on it; its protein half-life has been measured.
Gene: Protein-coding gene on chromosome 16 (3,581,181 to 3,611,606, reverse strand). Ensembl gene ENSG00000188827.
Subcellular location: Nucleus
Subcellular location (Human Protein Atlas): Nucleoplasm
Pathways (Reactome):
DNA Repair: Fanconi Anemia Pathway; Resolution of D-loop Structures through Holliday Junction Intermediates
Gene Ontology:
Molecular function: enzyme activator activity; protein binding; DNA binding
Biological process: DNA double-strand break processing involved in repair via single-strand annealing; DNA repair; double-strand break repair via homologous recombination; negative regulation of telomere maintenance via telomere lengthening; nucleotide-excision repair; positive regulation of telomere maintenance; response to intra-S DNA damage checkpoint signaling; t-circle formation; telomeric D-loop disassembly; DNA replication; positive regulation of t-circle formation; resolution of meiotic recombination intermediates
Cellular component: chromatin; chromosome, telomeric region; ERCC4-ERCC1 complex; Holliday junction resolvase complex; nuclear chromosome; nucleoplasm; Slx1-Slx4 complex; nucleus
Genetic constraint (gnomAD): Loss-of-function variants: 112 observed, 146.22 expected, observed/expected ratio (o/e) 0.77, 90% interval 0.66 to 0.9. The upper end of that interval is the gene's LOEUF score, 0.9, which puts it in group 3 of 6, group 1 being the genes least tolerant of losing a copy. Missense variants: 2,562 observed, 2,460.8 expected, observed/expected ratio (o/e) 1.04, 90% interval 1.01 to 1.08. Synonymous variants: 1,061 observed, 1,023.4 expected, observed/expected ratio (o/e) 1.04, 90% interval 0.99 to 1.09.
Gene-disease validity (ClinGen):
ClinGen rates the evidence that SLX4 causes each of these diseases.
Fanconi anemia complementation group P (autosomal recessive): Definitive.
hereditary breast carcinoma (autosomal dominant): Refuted. Breast carcinoma that has developed in relatives of patients with history of breast carcinoma.
familial ovarian cancer (autosomal dominant): No Known Disease Relationship. An instance of ovarian cancer that is caused by an inherited modification of the individual's genome.
Homologues: Orthologues: chimpanzee SLX4 (98% identical), macaque SLX4 (83% identical), dog SLX4 (61% identical), guinea pig SLX4 (60% identical), pig SLX4 (59% identical), rabbit SLX4 (59% identical), rat Slx4 (57% identical), mouse Slx4 (52% identical), tropical clawed frog slx4 (29% identical), zebrafish slx4 (23% identical), Caenorhabditis elegans him-18 (8% identical), zebrafish si:dkey-44g23.2 (4% identical).
Diseases named in the same sentence as SLX4 in open-access papers:
SLX4 is named in the same sentence as 48 diseases in open-access papers, as found by Europe PMC text mining. Sharing a sentence is not in itself a finding about the gene and the disease. The quoted sentences say what the papers report.
Fanconi anemia (58 papers, 2011 to 2026). Fanconi anemia (FA) is a hereditary DNA repair disorder characterized by progressive pancytopenia with bone marrow failure, variable congenital malformations and predisposition to develop hematological or solid tumors. "Mutations in SLX4 (FANCP) cause Fanconi anaemia, a disorder characterised by developmental abnormalities, anaemia, and increased cancer risk." (PMID 41309571, 2025). "Recent studies have reported mutations in the SLX4 gene in a new subtype of Fanconi anemia (FA), FA-P." (PMID 39684352, 2024). "SLX4 mutations have been identified in Fanconi anemia and the gene is also known as FANCP (, rev in)." (PMID 38828439, 2024). "The physiological role of SLX4 is underscored by the fact that biallelic mutations in SLX4 can lead to Fanconi anemia." (PMID 34804132, 2021). "Fanconi anaemia patient mutations in XPF often display substantial in-vitro activity but are resistant to activation by ICLR recruitment factor SLX4." (PMID 32111838, 2020). "Variant rs10138997 (FANCM) and variants rs3810812 and rs28516461 (SLX4) are Fanconi anemia (FA) disease associated (NCBI ClinVar)." (PMID 32708070, 2020). "Structure-specific endonuclease subunit (SLX4) encodes a Fanconi anemia-related protein that is required for repair of specific types of DNA lesions and critical for cellular responses to replication fork failure." (PMID 31248416, 2019). "Six patients had mutations in FANCA, FANCI, FANCL, FANCM and SLX4 genes, which are involved in Fanconi anemia (FA)." (PMID 28423363, 2017). "Surprisingly, SLX4 deficiency in humans leads to classical Fanconi anemia, and Slx4-deficient mice phenocopy many aspects of this human illness." (PMID 24726326, 2014). "Mutations in the SLX4 gene, which encodes for a scaffold protein involved in the repair of interstrand cross-links, have recently been identified in unclassified Fanconi anemia patients." (PMID 22401137, 2012). "Mutations in SLX4 result in a subtype of Fanconi anaemia in humans." (PMID 35412622, 2022). "Mutations in SLX4 are associated with a recessive human disorder, Fanconi anemia." (PMID 35412622, 2022). "Similarly, SLX4 has also been associated with onset of Fanconi anemia, which is also characterized by telomere lengthening." (PMID 33195511, 2020). "For instance, mutations in SLX4 have been found in patients with Fanconi anemia clinical features." (PMID 31936378, 2020). "In human, SLX4 is one of the genes mutated in Fanconi anemia (and is therefore also known as FANCP), a rare genetic disorder characterized by defective repair of replication-blocking inter-strand DNA crosslinks, genome instability, bone marrow failure and a high susceptibility to cancer." (PMID 30893921, 2019). "Mutations in SLX4 have been associated with Fanconi Anemia (group P)." (PMID 30995915, 2019). "Interestingly, SLX4 mutations have been associated to Fanconi anaemia, and are found in sporadic tumours as well." (PMID 28290553, 2017). "Though the family was nonsyndromic, we identified a combination of rare variants in Fanconi anemia (FA) genes FANCP/SLX4 (compound heterozygote - rs137976282/rs79842542) and FANCA (rs61753269) and a rare homozygous variant in the Holliday junction resolvase GEN1 (rs16981869)." (PMID 26201965, 2015). "Recent studies have reported mutations in SLX4 in a new subtype of Fanconi anemia (FA), FA-P." (PMID 23840564, 2013). "Moreover, individuals carrying mutations in SLX4 exhibit symptoms of Fanconi anemia, a syndrome characterized by chromosomal instability in humans." (PMID 22927825, 2012). "Prior studies found that the Fanconi anaemia patient mutation XPF L230P and C236R, as well as the synthetically generated mutations XPF G325E and XPF Δ323–326, show impaired interactions with SLX4, manifesting as recruitment or activation defects." (PMID 41402316, 2025). "SLX4 is also known as FANCP and is a part of the Fanconi Anemia DNA repair pathway alongside 15 other proteins." (PMID 39205287, 2024).
Fanconi anemia (continued). "The interaction between SLX4 and XPF is critical for the repair of DNA interstrand crosslinks and a subset of Fanconi anemia patients harbor mutations in SLX4/FANCP or XPF/FANCQ." (PMID 34804132, 2021). "The first clue that the SLX4 UBZ4 domains were physiologically relevant came from identifying Fanconi anemia patients carrying in-frame deletions of SLX4 that disrupted UBZ-1 and deleted UBZ-2." (PMID 34804132, 2021). "The results indicated a significant association between the Fanconi anemia genes (FANCM, FANCP/SLX4, FANCI) and the activity of alkylating agents, antifolates, topoisomerase II and DNA synthesis inhibitors." (PMID 27746730, 2016). "Due to involvement of FANCM, FANCJ and FANCP homologues (Mph1, Chl1 and Slx4), this pathway has been described as a Fanconi anemia-like pathway." (PMID 27636878, 2016). "SLX4, also known as BTBD12, was renamed FANCP, when biallelic mutations in the SLX4 gene were associated with Fanconi anemia (FA), an autosomal recessive genetic disorder characterized by congenital abnormalities, bone marrow failure and cancer susceptibility." (PMID 25496524, 2014). "Defects in SLX4, a scaffold for DNA repair nucleases, result in Fanconi anemia (FA), due to the defective repair of inter-strand DNA crosslinks (ICLs)." (PMID 24794496, 2014). "A mouse knockout of Slx4 also shows chromosomal instability phenotypes similar to those of Fanconi anemia in humans." (PMID 22927825, 2012). "These nucleases include XPF/ERCC1, MUS81/EME1, their regulator SLX4 (also known as the Fanconi Anemia gene FANCP), SNM1A and SNM1B." (PMID 23144634, 2012). "Furthermore, TELO2 and SLX4 are enriched in the Fanconi anemia pathway, which is primarily responsible for the repair of DNA strand cross-links, maintenance of genome stability, stabilization of replication forks, and regulation of cell division." (PMID 39457914, 2024). "Among these 14 pathways, four major pathways were enriched: SNARE interactions involved in the vesicular transport (BET1 and STX6), leishmaniasis (FCGR1A, CYBB, and FOS), hematopoietic cell lineages (FCGR1A, ITGA3, MME, and CD5) and Fanconi anemia pathway (SLX4, ATR, and TELO2)." (PMID 37601105, 2023). "The known functions of these genes cluster into two main functional families, 3 out of 8 are DNA repair genes associated with Fanconi anemia: FANCD2, SLX4, and FANCA, while 3 out the 8 are HLA genes comprising the major histocompatibility complex (MHC) involving immunity." (PMID 35962345, 2022). "For example, it would be interesting to determine whether Fanconi anemia patient cells that lack SLX4 are abnormally reliant on the SLX4IP-XPF-ERCC1 complex for genome stability." (PMID 34804132, 2021). "In addition, Slx4 is involved in interstrand cross-link (ICL) repair, and is also known as FANC-P, which is responsible for one subgroup of Fanconi anemia in humans." (PMID 27172214, 2016). "Both MUS81-EME1 and XPF-ERCC1 interact with FANCP/SLX4, a newly identified Fanconi anemia protein." (PMID 24170812, 2014). "SLX4 binds to three nucleases (XPF-ERCC1, MUS81-EME1, and SLX1), and its deficiency leads to genomic instability, sensitivity to DNA crosslinking agents, and Fanconi anemia." (PMID 24726326, 2014). "Pathway analyses with the KEGG and REAC databases revealed a significant enrichment of the Fanconi anemia (FA) repair pathway, with notable genes such as BRIP1 (FANCJ), FANCI, FANCA, SLX4 (FANCP), UBE2T (FANCT), and C19orf40 (FAAP24)." (PMID 38896450, 2024). "This critical repair step requires the endonuclease XPF (FANCQ)‐ERCC1, which is recruited to the ICL by the large scaffold protein SLX4 (FANCP), and depends on the activation of the Fanconi anemia pathway by ubiquitylation of the FANCI‐FANCD2 complex." (PMID 28292785, 2017).
Fanconi anemia (continued). "Recently, an Fanconi anemia (FA) protein, SLX4 (or BTBD12 or FANCP), that interacts with XPF-ERCC1, MUS81-EME1, and SLX1 was identified." (PMID 27228173, 2016). "SLX4 works with several DNA repair pathways, nonhomologous end joining, homologous recombination, Fanconi anaemia, nucleotide excision repair, and some nonspecific pathways." (PMID 35181726, 2022). "Relevant to the adaptation of TRD to arid conditions, ten selected genes (including SLX4, FANCF, FANCG, FANCI, ATR, and POLH) were related to the fanconi anemia pathway (bta03460, p < 0.01) involved in DNA repair, DNA replication fork stability, and other cellular processes." (PMID 33072165, 2020). "This analysis identified several novel ATR synthetic lethal partner genes involved in DNA damage/repair including those targeting components of the HR/Fanconi Anaemia pathway (FANCE, SLX4, PALB2), DNA mismatch repair (MSH4, PMS2) and trans-lesion synthesis (RAD18) pathways." (PMID 27958275, 2016).
breast carcinoma (24 papers, 2012 to 2025). "Conversely, SLX4 mutations were present in three of 89 (3%) pretreatment biopsies and 1.5% in The Cancer Genome Atlas (TCGA) breast cancer (BRCA)." (PMID 37488289, 2023). "SLX4 (FANCP) mutations have been observed in breast cancer, however it has been determined in multiple studies that this is not frequent enough to class FANCP as a susceptibility gene." (PMID 36046263, 2020). "Very recently, SLX4 has been established as a new FA gene raising the question of its implication in breast cancer risk." (PMID 22383991, 2012). "So far, while BRCA2, BRIP1, PALB2, and RAD51C are associated with high or moderate breast cancer risk, the impact of SLX4 on breast cancer remains to be measured." (PMID 22383991, 2012). "Thus, SLX4 mutation (c.1114C > T) segregated along with familiar breast cancer gene and caused breast cancer susceptibility." (PMID 34257587, 2021). "Overall, our study, in combination with other published work suggests that mutation in SLX4 may be associated with increased risk of breast cancer in a very small number of familial breast cancers." (PMID 23840564, 2013). "Loss-of-function mutations in SLX4 may contribute to the development of breast cancer in very rare cases." (PMID 23840564, 2013). "Among breast cancer subtypes, the top eight mutational rates were MAD2L2/FANCV (37.5%), FANCI (32%), ATR (32%), FAAP20 (30%), FAAP100 (28%), SLX4 (27%), FANCT (27%), and BRIP1 (26%) in breast invasive carcinoma NOS." (PMID 39421870, 2024). "We assessed cell viability in two breast cancer cell lines depleted for SLX4 and treated with different doses of DXd for 5 days." (PMID 37488289, 2023). "Mutations in other FA family members have been demonstrated to predispose to breast cancer, including PALB2 (FANCN), BRIP1 (FANCJ), RAD51C (FANCO), SLX4 (FANCP), and FANCM." (PMID 31320901, 2019). "So far, three truncating SLX4 mutations have been reported in 2,625 non-BRCA1/2 breast cancer patients in all published work, including this study." (PMID 23840564, 2013). "This study aimed at answering this question sequencing the entire coding region of SLX4 in 526 familial breast cancer cases from Italy." (PMID 22383991, 2012). "In this context, we sequenced the entire coding region and the intron-exon boundaries of SLX4 in 526 familial breast cancer cases from Italy." (PMID 22383991, 2012). "Likewise, HR−HER2-positive breast cancer showed more differentially mutated genes (ERBB2, PRKDC, PTEN and NEB) than HR−HER2-zero breast cancer (only SLX4) compared to HR−HER2-low breast cancer (3 vs 1)." (PMID 37264417, 2023). "Also included are breast cancer susceptibility proteins, such as BRCA1 (FANCS) and BRCA2 (FANCD1), and SLX4 (FANCP), a scaffold for endonucleases such as XPF (FANCQ)." (PMID 27760317, 2016). "Over the last year, five studies have investigated the role of SLX4 in familial BRCA1/2 mutation-negative breast cancer cases." (PMID 23840564, 2013). "Here we present our SLX4 sequencing results in 738 BRCA1/2 mutation-negative breast cancer patients and a functional analysis of select SLX4 variants." (PMID 23840564, 2013). "We sequenced the entire coding region of the SLX4 gene in 738 BRCA1/2 mutation-negative familial breast cancer patients and found 26 previously known and 14 novel coding variants." (PMID 23840564, 2013). "Our studies suggest that assessment of any SLX4 variants identified in breast cancers should include evaluation of their impact on sensitivity not only to ICL agents but also to CPT and Olaparib." (PMID 23840564, 2013). "A mutation analysis of SLX4 in German or Byelorussian familial cases of breast cancer without detected mutations in BRCA1 or BRCA2 has been completed, with globally negative results." (PMID 22401137, 2012).
breast carcinoma (continued). "The genomic region of SLX4, comprising all exons and exon-intron boundaries, was sequenced in 94 Spanish familial breast cancer cases that match a criterion indicating the potential presence of a highly-penetrant germline mutation, following exclusion of BRCA1 or BRCA2 mutations." (PMID 22401137, 2012). "Our results indicate that testing for SLX4 germline mutations is unlikely to be relevant for the identification of individuals at risk of breast cancer, at least in the Italian population." (PMID 22383991, 2012). "To determine if SLX4 is involved in breast cancer susceptibility, we sequenced the entire SLX4 coding region in 738 (270 Jewish and 468 non-Jewish) breast cancer patients with 2 or more family members affected by breast cancer and no known BRCA1 or BRCA2 mutations." (PMID 23840564, 2013). "The breast cancer susceptibility and Fanconi proteins FANCD1/BRCA2, the partner of BRCA2 (PALB2/FANCN), a helicase associated with BRCA1 (FANCJ/BACH1), and several newly identified components including FAN1, FANCO/RAD51C, and FANCP/SLX4 participate in the pathway to respond to and repair DNA damage." (PMID 22693661, 2012). "This might mean that SLX4 is not a breast cancer predisposition gene." (PMID 23840564, 2013). "Overall, while the results of this study do not identify clearly pathogenic mutations of SLX4 contributing to breast cancer risk, further genetic analysis, combined with functional assays of the identified rare variants, may be warranted to conclusively assess the potential link with the disease." (PMID 22401137, 2012). "We sequenced all exons and exon-intron boundaries of the SLX4 gene in 738 (270 Jewish and 468 non-Jewish) breast cancer patients with BRCA1/2 mutation-negative breast cancer and a family history of breast cancer with two or more additional affected individuals in the family." (PMID 23840564, 2013).